CDK4 (cyclin dependent kinase 4)
Diseases named in the same sentence as CDK4 in open-access papers (continued):
Sharing a sentence is not in itself a finding about the gene and the disease.
breast cancer (continued). "Second, acquired resistance to CDK4/6 inhibition in luminal breast cancers may be driven by cyclin E/CDK2 activity (facilitating S-phase entry despite CDK4/6 blockade), providing rationale for studying the inhibition of CDK2 in these tumors as well." (PMID 38047585, 2024). "High levels of CDK4/6 overexpression have been observed in patients with luminal (i.e., estrogen receptor (ER)–positive) breast cancer, the most common subtype, representing approximately 75% of all breast cancers." (PMID 38999983, 2024). "The introduction of these CDK4/6 inhibitors for clinical use constitutes a milestone in the treatment of breast cancer and may have broad ramifications for the management of other tumor types." (PMID 38605349, 2024). "The data from TROPiCS-02 have resulted in the inclusion of SG as a category I option in the 2023 NCCN Guidelines for Breast Cancer and its recommendation as a second-line treatment for HR+/HER2− breast cancer patients who have previously received endocrine therapy (ET) and CDK4/6 inhibitors." (PMID 38794221, 2024). "Efforts have been made to restore the crosstalk between DCs and CD4+ T cells by promoting DC maturation, which has shown promising results in conferring potent immunity in breast cancer with CDK4/6 inhibitors (CDK4/6i) and immune checkpoint blockade (ICB) therapy." (PMID 39188717, 2024). "For this reason, CDK4/6 has been explored as a potential therapeutic target for breast cancer." (PMID 38831405, 2024). "The combination of CDK4/6 and PI3K inhibitors resulted in the regression of breast cancer grafts with PIK3CA mutations, and the combination of PI3K, AKT, and mTORC1/2 inhibitors demonstrated increased efficacy in multiple preclinical models of breast cancer." (PMID 39544302, 2024). "Notably, targeting RET with selpercatinib in combination with CDK4/6i inhibited the growth of CDK4/6i-resistant cell lines and resensitized ER+ breast cancer patient-derived organoids resistant to CDK4/6i." (PMID 39931212, 2024). "Consequently, the advent of CDK4/6 inhibition has constituted a pivotal milestone in the realm of targeted breast cancer therapy." (PMID 38409585, 2024). "Moreover, several clinical trials have substantiated the antitumor efficacy of CDK4/6i in HR + /HER2+ breast cancer." (PMID 38409585, 2024). "Therefore, the inhibition of both CDK4/6 and ER have shown clinical efficacy in ER+ advanced breast cancer." (PMID 38409585, 2024). "Given this, we may need to improve the prognosis of HR+/HER2-low breast cancer patients who receive CDK4/6i and ET." (PMID 39267829, 2024). "CDK4/6 inhibitors are mostly applied to patients with HR+ breast cancer." (PMID 39000513, 2024). "Epigenetic YAP activation following CDK4/6 inhibitor treatment may be a common occurrence in patients with luminal breast cancer." (PMID 38622197, 2024). "This resulted in the approval of combined CDK4/6i and an aromatase inhibitor (AI) for ER+ advanced breast cancer as first-line treatment and as second-line therapy in combination with the selective estrogen-receptor degrader (SERD) fulvestrant following initial AI monotherapy." (PMID 39931212, 2024). "While preclinical studies demonstrated the efficacy of CDK4/6 inhibition in Rb-proficient human tumor xenograft models, the introduction of CDK4/6 inhibitors has significantly changed the management of endocrine-resistant ER+ breast cancer." (PMID 38275906, 2024). "Furthermore, the anti-HER inhibitor neratinib was administered to enhance the effectiveness of CDK4/6 inhibitor combined with endocrine therapy in HR+/HER2-low breast cancer by inhibiting the HER2 pathway and lowering HER2 mRNA expression." (PMID 39730704, 2024). "Hence, CDK4/6 emerges as an attractive target to enhance the survival prospects of HR + /HER2+ breast cancer patients." (PMID 38409585, 2024).
breast cancer (continued). "To investigate whether MAP3K3 inhibition suppresses YAP activity in breast cancer cells resistant to the CDK4/6 inhibitor palbociclib, we established palbociclib-resistant MCF7 (MCF7_PalR) and T47D (T47D_PalR) cell lines by chronic drug administration." (PMID 38622197, 2024). "The RIGHT Choice, a randomized, phase II, open-label, multicenter clinical trial presented at the 2022 San Antonio Breast Cancer Symposium (SABCS), offered the first head-to-head comparison of CDK4/6i plus ET versus CT in advanced HR + /HER2- breast cancer with life-threatening VC." (PMID 38409585, 2024). "To summarize, CDK4/6i have revolutionized the management of HR+ breast cancer." (PMID 38409585, 2024). "However, the specific mechanisms through which these two compounds regulate CDK4 signaling and their role in regulating breast cancer cell cycle remained unclear." (PMID 38215156, 2024). "However, in a large population of patients with metastatic ER+/HER2-negative breast cancer, even a small proportion of patients being treated with second-line CDK4/6 inhibitors still results in a substantial number of individuals overall." (PMID 39697231, 2024). "Moreover, we show that MAP3K3 inhibition, achieved through RNAi-mediated knockdown or pharmacological means, overcomes CDK4/6 inhibitor resistance in luminal breast cancer cells." (PMID 38622197, 2024). "Despite being the standard of care in ER+ breast cancer, the molecular underpinnings of the benefit achieved with the use of endocrine therapies and CDK4/6 inhibitors as well as the mediators of resistance to these agents remain largely unknown." (PMID 37914699, 2023). "mTORC1 inhibitors have been studied in combination with hormone therapy and/or CDK4/6 inhibitors in melanoma and breast cancer, although the exact mechanisms remain unclear." (PMID 37264081, 2023). "Src remains of interest as a target in breast cancer and, interestingly, one mechanism of CDK4/6 inhibitor resistance may involve downregulation of p27kip1, which occurs via phosphorylation of Src." (PMID 36859649, 2023). "In addition to alterations in major cell cycle regulators, CDK4/6 inhibitor resistance in breast cancer also involves various genomic alterations, with the RAS/MAPK and PI3K/AKT/mTOR pathways playing key roles." (PMID 37511548, 2023). "Since CDK4/6 inhibitors have made a significant impact on clinical outcomes in advanced breast cancer, targeting of other CDKs may lead to improved clinical outcomes in various cancers." (PMID 37111276, 2023). "However, for ER-positive breast cancers that arise after anti-estrogen preventive therapy, the combination of a different anti-estrogen drug plus a CDK4/6 inhibitor is often used for treatment." (PMID 37583424, 2023). "The difference in estimated median progression-free survival was greater in the ER-positive/PR-negative/HER2-negative tumor than in the ER-positive/PR-positive/HER2-negative tumor when CDK4/6 inhibitor was used for patients with advanced breast cancer (9.2 months vs 7.9 months)." (PMID 36869991, 2023). "Finally, there is preclinical data to support AR activation as a therapeutic strategy for ER + breast cancer, including ET and CDK4/6 inhibitor resistant ER + breast cancer models." (PMID 37035239, 2023). "This CDK4 selectivity suggests that abemaciclib may significantly reduce the growth of breast cancer cells." (PMID 37759823, 2023). "The second line may be the optimal setting for patients with HR+/HER2− advanced breast cancer to receive CDK4/6is, according to findings from the phase III SONIA trial presented at the 2023 ASCO Annual Meeting." (PMID 37759823, 2023). "We therefore focused on the role of CPVL in breast cancer resistance to CDK4/6 inhibitors." (PMID 36825764, 2023). "CDK4/6i treatment led to PARP1 upregulation in breast cancer patients and cells." (PMID 38037159, 2023).
breast cancer (continued). "To date, there have been no reported cases of osteopenia or osteoporosis in breast cancer patients caused by CDK4/6 inhibitor use, although more research is required." (PMID 37483519, 2023). "In this study, in silico techniques including molecular docking, MM-GBSA, and molecular dynamics were employed to identify compounds with multitarget inhibitory potentiality against CDK4/6 and aromatase for the treatment of estrogen receptor-positive breast cancer." (PMID 37682937, 2023). "We performed a prospective subgroup analysis of the Vax-On-Third-Profile study to investigate longitudinal changes in antibody titers following full-course of mRNA-BNT162b2 (tozinameran) immunization in patients with advanced breast cancer receiving CDK4/6 inhibitors or HER2-targeted agents." (PMID 38023235, 2023). "In another study, the combination of SFN and Withaferin A blocked cell cycle progression from the S to G2 phase in breast cancer cell lines by down-regulating cyclin D1, cyclin dependent kinase 4 (CDK4), and pRB with a concomitant increase in p21 and E2F mRNA levels." (PMID 36765652, 2023). "This study extends our understanding of real-world CDK4 and 6 inhibitor use in Japan, providing insight into current treatment practices for HR+, HER2− advanced breast cancer, specifically in relation to treatment patterns of CDK4 and 6 inhibitor use and their clinical outcomes." (PMID 36414795, 2023). "More recently, in the treatment of metastatic breast cancer, selective small molecule CDK4/6 inhibitors have also become increasingly effective, such as palbociclib, ribociclib and abemaciclib, which have been developed in metastatic luminal breast cancer." (PMID 37063263, 2023). "Thus, targeted therapy (trastuzumab or lapatinib) combined with CDK4/6 inhibitors is a promising strategy for the treatment of HER2-positive breast cancer." (PMID 37160904, 2023). "Therefore, CDK4/6 inhibitors combined with endocrine therapy have emerged as a main treatment strategy for HR+/HER2– breast cancer as a first or subsequent line of therapy." (PMID 38017459, 2023). "Even though CDK4/6i have shown significant clinical benefits in HR + breast cancer." (PMID 37475713, 2023). "In another study, it was demonstrated in both in-vitro and xenograft animal models that the combination of luteolin and indole-3-carbinol had a synergistic effect in restricting ERα-positive breast cancer by inhibiting the estrogen receptor alpha and the cyclin-dependent kinase 4/6 pathway." (PMID 37432206, 2023). "In this study, we retrospectively investigated the association between NOLUS and clinicopathological data from the patients treated with CDK4/6is in Japan, sponsored by the Kinki Breast Cancer Study Group-Translational Research (KBCSG-TR) to investigate the usefulness of NOLUS." (PMID 37486454, 2023). "Median TTD for all breast cancer drugs after starting a CDK4 and 6 inhibitor, assumed to correspond to the period up to implementation of best supportive care, was 36.0 months in the CDK4/6i cohort." (PMID 36414795, 2023). "Scores from the 150 ctDNA-based signatures (adjusted by TF) were evaluated in paired plasma samples (i.e., baseline versus post-treatment after progressive disease) in 7 patients with advanced HR+/HER2- breast cancer treated with endocrine therapy and a CDK4/6 inhibitor." (PMID 36859416, 2023). "However, FDA has recently approved the use of the CDK4/6 inhibitor abemaciclib for use in early breast cancer patients with one of the conditions being that Ki67baseline is > 20%." (PMID 37046348, 2023). "Furthermore, recent studies indicate that CDK4/6 is a crucial player in the initiation and development of breast cancer." (PMID 37711177, 2023). "Various clinical trials within the framework of the PALOMA, MONALEESA, and MONARCH study families form the basis for the FDA approvals, showing improved progression-free survival (PFS) and OS for treatment with CDK4/6 inhibitors and endocrine therapy in breast cancer patients." (PMID 36817127, 2023).
breast cancer (continued). "Effective ways to treat resistance to ETs and CDK4/6i is a high unmet need in ER+ breast cancer." (PMID 37725704, 2023). "Hence, these combined computational approaches will provide a better therapeutic potential for developing CDK4/6-aromatase dual inhibitors for HR+ breast cancer therapy." (PMID 36985460, 2023). "Indeed, FGFRs contribute to cyclin-dependent kinase 4/6 inhibitor (CDK4/6i) resistance and FGFR1 overexpression reduced the efficacy of CDK4/6i treatment for breast cancer patients enrolled in the MONALEESA-2 study." (PMID 37715207, 2023). "Notably, MONALEESA-3 is the only one of the CDK4/6i + fulvestrant trials which included a population of patients with advanced breast cancer in the first line of treatment." (PMID 37366894, 2023). "While CDK6/cyclin D3 is linked to the hematopoietic system and is crucial for healthy thymus development and the maturation of bone marrow hematopoietic stem cells, CDK4/cyclin D1 is related to cell proliferation and is essential for supporting the progression of breast cancer." (PMID 37759823, 2023). "Therefore, to fill this gap of knowledge, this study aims to investigate the effectiveness and safety of two CDK4/6 inhibitors, palbociclib and ribociclib, for real-world breast cancer patients’ data from the clinical practice in the state of Qatar." (PMID 38162489, 2023). "CDK4 inhibitors are currently approved for treatment in advanced breast cancer." (PMID 37111276, 2023). "We reported the experience of the EADV task force “dermatology for cancer patients” who examined the largest case series regarding the spectrum of skin toxicities recorded in breast cancer patients undergoing treatment with CDK4/6i, including each of the approved and available CDK4/6i." (PMID 37509319, 2023). "It has also been shown that miR-34b/c suppresses CDK4/6 expression in breast cancer cell lines." (PMID 37443682, 2023). "Medication adherence to CDK4/6 inhibitors such as palbociclib, prescribed as a cyclic oral anticancer therapy in women diagnosed with advanced breast cancer, may be suboptimal." (PMID 36612312, 2023). "Three CDK4/6 inhibitors (abemaciclib, ABE; ribociclib, RIB; palbociclib, PAL) have been approved for the treatment of hormone-receptor-positive, HER2-negative, advanced breast cancer and more CDK4/6 inhibitors have entered clinical trials for the treatment of various cancer types." (PMID 36755269, 2023). "Palbociclib (PBC) is an FDA-approved CDK4/6 inhibitor used for breast cancer treatment." (PMID 37896189, 2023). "Thus, PRMT5 is an actionable therapeutic vulnerability in breast cancers of this genotype and potentially fill an unmet need for patients with acquired resistance to CDK4/6i." (PMID 37502925, 2023). "Most notably, in this clinical context, Mps1 inhibition has been shown to be well tolerated in patients and has recently received FDA fast-track designation for the treatment of adult patients with ER + /HER2 − advanced breast cancer after progression to CDK4/6 inhibitors and hormone therapy." (PMID 37058263, 2023). "Given that palbociclib induces cell cycle arrest and senescence as a primary mechanism to impede cell growth, we postulate that O-GlcNAc-MITF assumes a crucial role in modulating palbociclib resistance through senescence in breast cancer patients undergoing CDK4/6i therapy." (PMID 37886470, 2023). "YB-1 phosphorylation may remove the blocking effect of CDK4/6i on the G1/S phase transition and lead to the occurrence of CDK4/6i resistance in breast cancer." (PMID 38037159, 2023). "Interesting, insights from breast cancer cell research revealed that SFN orchestrates DNA methylation through the modulation of DNA methyltransferase and histone deacetylase levels, coupled with the downregulation of cyclin D1, CDK4, and pRB, thereby promoting breast cancer cell apoptosis." (PMID 37836745, 2023).
breast cancer (continued). "Owing to a relatively high cost of treatment with CDK4/6 inhibitors in Poland (vs. previous treatments), the reimbursement is offered only as part of the drug program of the Ministry of Health, “Treatment of breast cancer”." (PMID 36831045, 2023). "Whether tRF-16-K8J7K1B plays a similar role in breast cancer treated with aromatase inhibitors or CDK4/6 inhibitors remains unknown and requires further investigation." (PMID 36765853, 2023). "CDK4/6 inhibitors have changed the treatment landscape for ER+/HER2− advanced breast cancers." (PMID 37958338, 2023). "Clinical trials studying the application of CDK4/6 inhibitors in HER2+ breast cancer." (PMID 38293701, 2023). "Novel, unpublished data from the team suggest that γδ T cells may be involved in the resistance of patients with HR+ breast cancer to CDK4/6 inhibitors." (PMID 37347257, 2023). "In breast cancer cells expressing high levels of CDK4, we confirm this hypothesis and develop a high-throughput compatible assay that quantifies genetically modified CDK6 variants and inhibitors." (PMID 36884374, 2023). "Thus, combining CDK4/6 inhibitors with aromatase inhibitors has emerged as a crucial treatment strategy for this type of breast cancer." (PMID 37682937, 2023). "Preclinical work has demonstrated that tumor cell proliferation in breast cancer is significantly driven by upregulation of the cyclin D–CDK4/6-axis, and CDK4/6-inhibitors induce cytostasis through cell-cycle arrest in the G1 phase leading to in-growth inhibition." (PMID 37760527, 2023). "Given the increased use of CDK4 and 6 inhibitors in breast cancer, an important question is whether CDK4 inhibition impairs β cell function or differentiation." (PMID 37712417, 2023). "Anti-HER2 therapy could lead estrogen receptor (ER) shifting into cell nucleus in HER2+/HR+ breast cancer while CDK4/6 inhibitor could reverse the nuclear translocation of ER." (PMID 36602226, 2023). "Despite this and other unknowns, our data suggest that a program of cellular senescence may influence the response of HR+HER2− breast cancer to RT when combined with CDK4/6 inhibitors." (PMID 36765430, 2023). "The development of novel agents such as HER2-targeting monoclonal antibodies, antibody–drug conjugates (ADC), and cyclin-dependent kinase 4/6 (CDK4/6) inhibitors has dramatically improved the survival outcome of hormone receptor (HR)-positive breast cancer and HER2-positive breast cancer." (PMID 36836059, 2023). "Given the role of CDK4 inhibitors in breast cancer, further investigation into the role of CDK4 in regulating the target size of cells is necessary, as it may directly link metabolic regulation of cell size to cancer." (PMID 37649668, 2023). "The FDA has warned that certain patients with advanced breast cancer who are being treated with CDK4/6 inhibitor, palbociclib, ribociclib, or abemaciclib may experience a rare but serious lung inflammation." (PMID 37415164, 2023). "ACK1 inhibitor, (R)-9b could be a novel therapeutic option for the breast cancer patients that have developed resistance to CDK4/6 inhibitors." (PMID 37330596, 2023). "Recently, specific CDK4/6 inhibitors have been developed and used for advanced breast cancer." (PMID 37198667, 2023). "We also found that CDK4/6i treatment led to PARP1 upregulation in breast cancer patients and cells." (PMID 38037159, 2023). "Cyclin D1 and CDK4 contribute to breast tumorigenesis through their interaction with the cell cycle and promote proliferation in endocrine-resistant breast cancer cells and, together with Rb, potentially influence breast cancer pathogenesis and progression." (PMID 37369022, 2023). "The primary objective of this study was to describe the demographics and characteristics, treatment patterns, and clinical outcomes of Japanese patients with advanced HR+, HER2− breast cancer who were prescribed CDK4 and 6 inhibitors, using a large claims-based database." (PMID 36414795, 2023).